OLA1 (Obg like ATPase 1)
Description:
Hydrolyzes ATP, and can also hydrolyze GTP with lower efficiency. Has lower affinity for GTP.
Synonyms: DOC45; GTPBP9; PTD004; GBP45; GTBP9
Tractability: Small molecule: a structure with a bound ligand is known; a high-quality ligand is known. Antibody: its Gene Ontology location is reachable by antibodies, with high confidence. PROTAC: ubiquitination databases record sites on it; its protein half-life has been measured; a small molecule that binds it is known.
Target class: Enzyme; Hydrolase
Gene: Protein-coding gene on chromosome 2 (174,072,447 to 174,248,608, reverse strand). Ensembl gene ENSG00000138430.
Subcellular location: Cytoplasm; Nucleus; Nucleus, nucleolus
Subcellular location (Human Protein Atlas): Cytosol
Pathways (Reactome):
Hemostasis: Platelet degranulation
Gene Ontology:
Molecular function: ATP binding; ATP hydrolysis activity; cadherin binding; protein binding; GTP binding; ribosomal large subunit binding; ribosome binding
Biological process: ATP metabolic process
Cellular component: cytoplasm; cytosol; extracellular exosome; membrane; extracellular region; platelet alpha granule lumen; nucleolus; nucleus
Genetic constraint (gnomAD): Loss-of-function variants: 7 observed, 26.61 expected, observed/expected ratio (o/e) 0.26, 90% interval 0.15 to 0.49. The upper end of that interval is the gene's LOEUF score, 0.49, which puts it in group 2 of 6, group 1 being the genes least tolerant of losing a copy. Missense variants: 225 observed, 309.46 expected, observed/expected ratio (o/e) 0.73, 90% interval 0.65 to 0.81. Synonymous variants: 94 observed, 101.09 expected, observed/expected ratio (o/e) 0.93, 90% interval 0.79 to 1.1.
Homologues: Orthologues: chimpanzee OLA1 (100% identical), dog OLA1 (100% identical), rabbit OLA1 (100% identical), guinea pig OLA1 (99% identical), mouse Ola1 (99% identical), pig OLA1 (99% identical), rat Ola1 (98% identical), macaque OLA1 (92% identical), tropical clawed frog ola1 (75% identical), Drosophila melanogaster CG1354 (73% identical), Caenorhabditis elegans ola-1 (67% identical).
Diseases named in the same sentence as OLA1 in open-access papers:
OLA1 is named in the same sentence as 37 diseases in open-access papers, as found by Europe PMC text mining. Sharing a sentence is not in itself a finding about the gene and the disease. The quoted sentences say what the papers report.
breast carcinoma (12 papers, 2015 to 2024). "For example, DNAJC1 and OLA1 (which interacts with BRCA1) have been linked to breast cancer in cancer GWAS studies." (PMID 39535534, 2024). "A recent investigation in a breast cancer cell line demonstrated a point mutation (E168Q) in the OLA1 gene, which impaired its ability to bind BRCA1." (PMID 38889130, 2024). "OLA1 deficiency attenuates tubulin formation and thus regains the sensitivity of paclitaxel in breast cancer." (PMID 32528278, 2020). "Our initial goal was to define the mechanisms underlying OLA1 KD-promoted tumor growth, which was initially discovered in a breast cancer model." (PMID 26655089, 2016). "According to previous studies, OLA1 can interact with BRCA1 to regulate the centrosome number, which promotes the proliferation of breast cancer cells; OLA1 deficiency causes p21 accumulation which leads to stunted growth and frequent perinatal lethality in mouse embryonic development." (PMID 35440019, 2022). "Our group demonstrated that human OLA1 functions as an intrinsic regulator in cellular stress responses such as oxidative stress and heat shock, and down-regulation of OLA1 causes changes in cell migration and invasiveness in cultured human breast cancer cells." (PMID 26863455, 2016). "Therefore, this evidence leads us to believe that the chemoresistance of breast cancer cells caused by OLA1 may be achieved through the TGF-β/Smad pathway." (PMID 32528278, 2020). "For example, another point mutation in OLA1 (E168Q) prevents it from forming a complex with BRCA1 and BARD1 and is associated with poor outcomes in breast cancer." (PMID 38889130, 2024). "A point mutation (E168Q) in the OLA1 gene is linked to apoptosis, preventing the formation of a complex with BRCA1 and BARD1, and is associated with poor outcomes in breast cancer." (PMID 38889130, 2024). "In the TCGA dataset, C11orf1, OLA1, RPL31, SPDL1 and IL33 were identified to be associated with prognosis of breast cancer." (PMID 35761863, 2022). "Our results indicate OLA1 can be developed as a novel valuable target for an improvement of breast cancer chemotherapy." (PMID 32528278, 2020). "Decreased level of Bcl-2 and the increased levels of Bax and Caspase-3 were also observed, suggesting that knock down of OLA1 also promoted the sensitivity of breast cancer cells with intrinsic resistance to chemotherapy." (PMID 32528278, 2020). "In this study, we show that OLA1 is positively correlated with the development of drug resistance by inducing the EMT process through activation of TGF-β/Smad signaling pathway in breast cancer." (PMID 32528278, 2020). "OLA1 target γ-tubulin to depolymerization microtubules and avoid cell cycle block in paclitaxel-resistant cancer cells instead of tamoxifen resistant breast cancer cells." (PMID 32528278, 2020). "Our study provides a novel insight into revealing the distinct role of OLA1 in tamoxifen and paclitaxel resistant breast cancer." (PMID 32528278, 2020). "In this study we investigated the regulatory role of Obg-like ATPase 1 which is involved in multiple uses of drug resistance against breast cancer." (PMID 32528278, 2020). "We demonstrated that OLA1 was highly correlated with either acquired or intrinsic resistance of breast cancer." (PMID 32528278, 2020). "A series of in vitro assays was performed in the cells with RNAi-mediated knockdown to expound the regulatory function of OLA1 in breast cancer." (PMID 32528278, 2020). "Through matching with The Cancer Genome Atlas (TCGA) normal and Genotype-Tissue Expression (GTEx) data, we found that OLA1 is significantly upregulated in breast cancer (N=1085) compared to their paired normal tissue (N=291)." (PMID 32528278, 2020). "Therefore, let us justify the hypothesis that OLA1 may be associated with breast cancer resistance." (PMID 32528278, 2020).
breast carcinoma (continued). "We found that OLA1 has a ubiquitous expression in the brain, thyroid, and 25 other tissues from the body map, and is highly expressed in breast cancer, pancreatic cancer, colorectal cancer, and other cancer tissues." (PMID 32528278, 2020). "Our study provides a novel insight that reveals the role of OLA1 in tamoxifen and paclitaxel resistant breast cancer." (PMID 32528278, 2020). "Our findings revealed that OLA1 enhanced the anti-apoptotic ability and elucidated a regulatory role of OLA1 in promoting chemotherapy resistance of breast cancer." (PMID 32528278, 2020). "In OLA1-knockdown (OLA1-KD) human breast cancer cells, the ISR signaling in response to cellular stresses is attenuated, as evidenced by reduced expression of ATF4, a surrogate marker of ISR, and hypophosphorylation of eIF2α." (PMID 26655089, 2016). "Based on analyses of 160 cases of breast cancer, we found that cancers with lower OLA1 protein expression have a worse prognosis than cancers with higher OLA1 levels, indicating that OLA1 plays a negative role in cancer progression rather than tumorigenesis." (PMID 26655089, 2016). "In orthotopic breast cancer models, OLA1-KD tumors have markedly increased potential to spread to LNs and lungs." (PMID 26283179, 2015). "This is consistent with the fact that lower OLA1 mRNA levels were correlated with decreased overall survival in TCGA breast cancer patients." (PMID 26283179, 2015). "Blockage of OLA1 may be a potential method to improve the survivability of chemoresistant breast cancer patients." (PMID 32528278, 2020). "We hypothesize that OLA1 may regulate paclitaxel resistance of breast cancer by interfering tubulin expression." (PMID 32528278, 2020). "Breast cancer-derived BARD1 variants C645R, V695L, and S761N show decreased association with OLA1." (PMID 32722046, 2020). "The mechanism of OLA1 participation in the resistance of paclitaxel in breast cancer was drawn." (PMID 32528278, 2020). "According to reports, decreased OLA1 expression weakens breast cancer cell motility and invasion." (PMID 32528278, 2020). "Our data suggest that OLA1 may be developed as a potential target to improve chemotherapy of patients with breast cancer." (PMID 32528278, 2020). "In our results, we demonstrated that OLA1 is a positive regulator of the EMT process regardless in the paclitaxel acquired resistance (MCF-7-PTR) cell or endogenous drug resistance cell (MDA-MB-231) in breast cancer." (PMID 32528278, 2020). "Finally, we observed a significant association between lower OLA1 expression and worse outcome in patients with breast cancer, indicating the significance of OLA1 in the prognosis of breast cancer." (PMID 26283179, 2015). "From these data, low OLA1 expression may represent a novel prognostic factor for breast cancer, especially for patients undergoing adjuvant chemotherapy." (PMID 26283179, 2015). "Therefore, we believe that OLA1 may be involved in paclitaxel resistance due to the interaction with γ-tubulin in breast cancer." (PMID 32528278, 2020). "The V695L variant shows loss of direct binding to OLA1 and decreased centrosomal localization and centrosome amplification by its overexpression; in addition, the variant fails to rescue the centrosome amplification induced by BARD1 knockdown in breast cancer cells." (PMID 32722046, 2020). "As reported, OLA1 was over expressed in a variety of malignant tumors including CRC, and was an important gene in regulating the growth and metastases in lung cancer and breast cancer." (PMID 35440019, 2022). "Thus far, there is no report showing whether OLA1 is associated with breast cancer drug resistance." (PMID 32528278, 2020). "OLA1 with the E168Q variant, which is identified in breast cancer cell lines, fails to bind to the N-terminal region of BRCA1 and rescue OLA1 knockdown-induced centrosome amplification." (PMID 32722046, 2020).
breast carcinoma (continued). "However, OLA1 and TGF β 1, SMAD3 SMAD4 has a strong positive correlation in the breast cancer tissue of the TCGA database (right)." (PMID 32528278, 2020). "We recently reported that knockdown of OLA1 in breast cancer cells (MDA-MB231) reduces apoptosis without affecting proliferation, resulting in enhanced late-stage tumor growth." (PMID 26655089, 2016).
colorectal cancer (11 papers, 2016 to 2024). A primary or metastatic malignant neoplasm that affects the colon or rectum. "The N6-methyladenosine reader IMP2 stabilizes the ZFAS1/OLA1 axis and activates the Warburg effect, which is implicated in colorectal cancer." (PMID 36175504, 2022). "m6A modification promotes mitochondrial energy metabolism in the pathogenesis of colorectal cancer by both stabilizing the ZFAS1/OLA1 axis and activating the Warburg effect." (PMID 36175504, 2022). "The importance of well-balanced Ola1-levels is further highlighted by the observation that Ola1 is up-regulated in various human tumours, such as colorectal carcinoma and ovarian and lung cancer." (PMID 35056463, 2021). "In addition, we analyzed the OLA1 protein expression in eight colorectal cancer cell lines by western blot, and the result indicated that OLA1 was high expression in most of these cell lines." (PMID 35440019, 2022). "Collectively, these data demonstrated that OLA1 can promote colorectal cancer cell growth in vitro." (PMID 35440019, 2022). "Obg-like ATPase 1 (OLA1) is a highly conserved GTPase, which was over expressed in a variety of malignant tumors, but its role in colorectal cancer (CRC) was poorly studied." (PMID 35440019, 2022). "In colorectal cancer, overexpression of the m6A reader IMP2 (IGF2BP2) stabilizes the ZFAS1/OLA1 axis, thereby increasing OLA1 recruitment, ATP hydrolysis, and glycolysis; activating the Warburg effect; and enhancing cancer cell proliferation and colony formation." (PMID 36525280, 2023). "In colorectal cancer, the overexpression of m6A reader IMP2 (IGF2BP2) can stabilize ZFAS1/OLA1 axis, which increases the recruitment of OLA1, ATP hydrolysis and glycolysis, activates Warburg effect, and enhances cell proliferation and colony formation of cancer cells." (PMID 35022030, 2022).
lung carcinoma (7 papers, 2016 to 2022). "We found that expression of OLA1 was negatively correlated with E-cadherin, the EMT marker, in lung cancer tissues, and high-level expression of OLA1 was associated with more advanced TNM stages, lymph node metastasis and poor prognosis." (PMID 26863455, 2016). "In order to establish the association between OLA1 expression status and overall survival (OS) in patients with lung cancer, we did a meta-analysis of OLA1 expression among 1928 lung cancer patients using the KM plotter software." (PMID 26863455, 2016). "In this study, we used the Kaplan-Meier plotter search tool to show that increased expression of OLA1 mRNA was significantly associated with shorter overall survival in lung cancer patients." (PMID 26863455, 2016). "In the present study, we aimed to investigate the clinical relevance of OLA1 in lung cancer and the underlying mechanisms." (PMID 26863455, 2016). "Because loss of the epithelial marker E-cadherin is a characteristic of EMT, we hypothesized that overexpression of OLA1 in lung cancer cells might cause downregulation of E-cadherin and progression of EMT, thus contributing to the acquisition of more aggressive and metastatic phenotype." (PMID 26863455, 2016). "Dysregulated OLA1 has been observed in various types of human malignant tumors including lung cancer, gastric cancer, oral cancer, and CRC." (PMID 34743750, 2021). "It was demonstrated that in lung cancer, OLA1 modulated EMT through GSK3β/Snail/E-cadherin, thereby modulating the invasion and metastasis of lung cancer." (PMID 35111070, 2021). "One previous report indicated that OLA1 is overexpressed in colon, stomach, ovarian, uterine, and lung cancers at the mRNA level and in colon cancer at the protein level compared to its expression in normal tissue counterparts." (PMID 32045367, 2020). "In summary, our results revealed that OLA1 is a novel endogenous suppressor of GSK3β, and through inhibiting the GSK3β/Snail/E-cadherin signaling, OLA1 positively regulates the EMT process in lung cancer cells." (PMID 26863455, 2016). "We conclude that OLA1 contributes to the EMT of lung cancer cells through regulating the GSK3β/Snail/E-cadherin signaling pathway." (PMID 26863455, 2016). "To explore the clinical implication of OLA1 in human lung cancer, we performed immunohisochemical (IHC) analysis with a lung tissue microarray." (PMID 26863455, 2016). "One previous report indicated that OLA1 is overexpressed in colon, stomach, ovary, uterus, and lung cancers at the mRNA level, and in colon cancer at the protein level, compared to their normal tissue counterparts." (PMID 26863455, 2016). "This study also demonstrated that high-level expression of OLA1 is associated with lymph node metastasis, advanced TNM stages, and poor prognosis in lung cancer including NSCLC." (PMID 26863455, 2016). "By immunohistochemical analysis we discovered that levels of OLA1 protein in lung cancer tissues were positively correlated with TNM stage and lymph node metastasis, but negatively correlated with the epithelial-mesenchymal transition (EMT) marker E-cadherin." (PMID 26863455, 2016). "In this study, we found a higher expression of OLA1 in lung squamous cell carcinoma than in other histological types among 110 lung cancer samples from a commercial tissue array." (PMID 26863455, 2016). "Further research is needed to evaluate the role of OLA1 in different histological types of lung cancer." (PMID 26863455, 2016). "Moreover, OLA1 contributes to EMT in lung cancer by modulating the GSK3β/Snail/E-cadherin signaling." (PMID 32528278, 2020). "Interestingly, in the present study, we established a strong inverse correlation between OLA1 expression and E-cadherin protein staining for all histological types of lung cancer." (PMID 26863455, 2016).
lung carcinoma (continued). "We compared the staining of OLA1 and E-cadherin among all 110 cancer cases, and found that the OLA1 levels were inversely correlated with the levels of E-cadherin within the same tumor tissue for all histological types of lung cancer." (PMID 26863455, 2016). "In this report, we demonstrated a positive role of OLA1 in cancer progression in lung cancer." (PMID 26863455, 2016).
colon cancer (5 papers, 2015 to 2022). "OLA1-KD tumors in the H116 colon cancer model showed markedly decreased eIF2α at Ser-51 (eIF2α-p) and reduced GSK3β-p, indicating hypoactive ISR and hyperactive GSK3 signaling." (PMID 26655089, 2016). "In these two pairs of colon cancer cell lines (Hct116 and Lovo), we found CA9 mRNA decreased in both Hct116 and Lovo OLA1-KO cell lines." (PMID 35440019, 2022). "Furthermore, using xenograft models of colon cancer (H116) and ovarian cancer (SKOV3), we established a correlation among downregulation of OLA1, over-activation of the positive feedback loop as indicated by under-phosphorylation of I-2, and more aggressive tumor growth." (PMID 26655089, 2016).
ovarian carcinoma (4 papers, 2016 to 2024). A malignant neoplasm originating from the surface ovarian epithelium. "OLA1 has been shown to be associated with hereditary breast and ovarian cancers as well as with a poor prognosis of HCC." (PMID 38540416, 2024). "In breast and ovarian cancer cells, OLA1 directly bound to the amino-terminal region of BRCA1 and γ-tubulin, resulting in centrosome regulation." (PMID 32045367, 2020).
hepatocellular carcinoma (3 papers, 2020 to 2025). A malignant tumor that arises from hepatocytes. "Moreover, OLA1 promotes proliferation of hepatocellular carcinoma cells by binding with p21 and upregulating CDK2 expression." (PMID 36232807, 2022). "However, the relationship between OLA1 and hepatocellular carcinoma (HCC) remains unclear." (PMID 32045367, 2020).